CAT (catalase)
Diseases named in the same sentence as CAT in open-access papers (continued):
Sharing a sentence is not in itself a finding about the gene and the disease.
ischemia (continued). "Resveratrol can reduce intestinal ischemia-reperfusion injury by activating the SIRT3/FoxO3a pathway, increasing the expression of SOD2 and catalase, reducing ROS and LPO production, compensating for the GSH/GPX4 pathway and inhibiting ferroptosis." (PMID 37858064, 2023). "Ischaemia and I/R-induced decline in SOD, catalase, GPx, and GST activities were significantly blunted by atorvastatin treatment." (PMID 36200598, 2022). "Ischaemia and I/R significantly reduced the activities of SOD, catalase, GPx, and GST in the ovarian tissues compared with the sham group, and sham and ischaemia groups respectively." (PMID 36200598, 2022). "In contrast, a beneficial effect of RVT is that pretreatment of animals with RVT before ischemia not only effectively reduces As and MDA levels, but also enhances the anti-oxidant activities of CAT and SOD in the ischemic brain." (PMID 34679650, 2021). "Changes in tissue antioxidant enzyme activities (CAT, SOD, and GSH-Px) and changes in the tissue levels of MDA in the ischemia/reperfusion group demonstrated a significant ischemia/reperfusion injury due to ovarian torsion." (PMID 32692796, 2020). "The secondary outcome was to compare the measurements of TAS, total oxidant status (TOS), ischemia-modified albumin (IMA) level, and catalase (CAT) level before ischemia onset (t1) and at the t2 and t3 time points." (PMID 31655508, 2019). "Recent evidence obtained using genetically-engineered animal models demonstrates the importance of catalase and SOD in protecting the myocardium against ischemia damage." (PMID 29135932, 2017). "Our results demonstrate that while the ischemia process decreases the expression of SOD-Cu2+/Zn2+, SOD-Mn2+ and catalase, the expression of SOD-Cu2+/Zn2+ increases significantly as a result of the treatments with foliar extracts." (PMID 29135932, 2017). "Imipramine, which showed good neuroprotective properties, enhances PEP-1-catalase in astrocytes, leading to neuroprotection in the hippocampal CA1 region in an ischemia model." (PMID 29259169, 2017). "Enzyme catalase activity dropped after AKI induction, while TEMPOL treatment significantly elevated its activity (P < 0.05) 24 hours after ischemia." (PMID 25050356, 2014). "The effect of GA on cardiac ischemia-reperfusion injury attributed to mitigating levels of CPK, CK-MB, LDH, MDA, infarct size, mPTPs opening and preservation of cell membrane, enhacement of SOD, CAT, GPx activity and coronary blood flow." (PMID 31921604, 2020). "First, apelin reduces ischemia/reperfusion injury-induced oxidative stress by increasing the activity of antioxidant enzymes in kidneys, such as superoxide dismutase (SOD), catalase (CAT) and glutathione peroxidase (GSH-Px)." (PMID 28167898, 2017). "There was not a remarkable difference between ischemia and treatment group since the treatment group did not have high CAT level obtained by Taurine." (PMID 21418563, 2011). "Our main results were as follows: 1) the CAT level decreased in Group C, whereas it remained the same in Group P; 2) the TOS decreased in Group P, whereas it increased in Group C; and 3) in Group P, the TAS value in the reperfusion period was higher than that in the ischemia period." (PMID 31655508, 2019). "In this sense, the Person correlations between cardiac and vascular sympathetic modulation and LV oxidative stress evaluations (CAT, superoxide anion and GSH/GSSG) found in the present study reinforce the role of the autonomic nervous system in the management of cellular responses to ischemia." (PMID 25301475, 2014). "This was validated by an increased H2O2 (Amplex red staining on kidney sections) in vehicle-treated mice at the end of ischemia, but not in GC7-treated mice, suggesting efficient transformation of H2O2 in H2O by catalase." (PMID 40789258, 2025).
Cognitive impairment (62 papers, 2014 to 2026). Abnormal cognition is characterized by deficits in thinking, reasoning, or remembering. "It was observed that prescription of phenolic extract of purslane containing indoline amides to mice with a cognitive deficit caused a significant increase in lifespan, spatial memory, learning ability, and CAT level in the brain and plasma." (PMID 36594059, 2023). "Thus, it is well-established that increased ROS and MDA levels, or reduced levels of antioxidants like SOD, GPx, and catalase, signify mitochondrial dysfunction and oxidative stress, which is also associated with cognitive impairment." (PMID 40894223, 2025). "In addition, cognitive deficits, especially impaired visual-spatial abilities, may be associated with abnormal CAT and GSH-Px activities." (PMID 35757215, 2022). "The cognitive impairment induced after DOX administration was observed to be associated with intense oxidative damage, as evidenced by decreased GSH, SOD, and CAT levels and increased MDA levels." (PMID 40358798, 2025). "Administration of quercetin, another antioxidant, in a rodent TBI-model reduced cognitive deficit and increased catalase and SOD antioxidant activity in the hippocampus." (PMID 40563779, 2025). "An abnormal increase in ROS and MDA, and a decrease in antioxidant activity (SOD and CAT) indicates that cells are suffering from oxidative stress, which is considered one of the main factors in ischemic cerebral damage and cognitive impairment." (PMID 38214766, 2024). "In the current study, it is likely that the reduction of catalase activity has played a remarkable role in the pathogenesis of brain injuries and cognitive deficits in rats subjected to recurrent severe hypoglycemia." (PMID 39004753, 2024). "However, because catalase is a key antioxidant defense enzyme, a decrease in catalase activity in the brain has been linked to an increase in oxidative stress, which may contribute to cellular damage and cognitive impairments." (PMID 37240148, 2023). "AA reduced MDA levels and increased the levels of antioxidant enzymes including superoxide dismutase, catalase, and glutathione peroxidase against oxidative stress and cognitive impairment induced by quinolinic acid and aluminum chloride (AlCl3) in rats." (PMID 37608290, 2023). "Plasma levels and the activity of other enzymatic antioxidants, such as extracellular superoxide dismutase, catalase, and glutathione peroxidase, were shown to decrease progressively according to the severity of the cognitive impairment." (PMID 35456047, 2022). "In this study, a superoxide dismutase (SOD) and catalase (CAT) containing poly (lactic-co-glycolic acid) (PLGA) meso-particles (PLGA@SOD-CAT) were prepared to attenuate cognitive impairment via inhibiting oxidative stress in rats." (PMID 33614079, 2021). "HBOT attenuated D-gal-induced cognitive impairment by reducing oxidative stress in hippocampus via the increase of superoxide dismutase, glutathione peroxidase, and catalase levels in hippocampus." (PMID 35822043, 2021). "Similar to this study, walnut consumption restored SOD, glutathione peroxidase (GPx), and catalase activities in scopolamine-induced cognitive impairment in rats." (PMID 33053754, 2020). "The increase in CAT and SOD1 in the head is particularly important because neural tissues are highly sensitive to oxidative stress, and reduced antioxidant defense has been associated with cognitive impairments in bees exposed to pesticides." (PMID 41200016, 2025). "This study was designed to determine the Murraya koenigii leaves’ effect on Alloxan-induced cognitive impairment in diabetic rats and the contents of oxidative stress biomarkers, catalase, reduced glutathione, and glutathione reductase in brain tissue homogenates." (PMID 36937470, 2023). "Thus, the involvement of oxidative stress in BPA induced cognitive impairment was assessed using various parameters like catalase, SOD and LPO in the hippocampal region of mice." (PMID 31064381, 2019).
Cognitive impairment (continued). "Furthermore, saffron significantly increased GSH, SOD, and CAT but remarkably decreased cognitive deficit, serum TNF-α, and induced nitric oxide synthase (iNOS) activity in hippocampus tissue." (PMID 25114929, 2014). "Animal experiments showed that PN ameliorated depressive mood and cognitive deficits in sleep-deprived mice, upregulated the serum activities of superoxide dismutase (SOD), glutathione (GSH), and catalase (CAT), and downregulated malondialdehyde (MDA) levels." (PMID 40076470, 2025). "Furthermore, our findings align with the notion that OVX-induced cognitive impairment is caused by recurrent stress triggering the excessive formation of free radicals and the inhibition of antioxidant systems, such as superoxide dismutase (SOD) and catalase (CAT) activities." (PMID 39338344, 2024). "The adverse effect of high Gal on cellular antioxidants (SOD, catalase, and GSH-Px), generation of free radicals, and induction of oxidative stress, which leads to cognitive disorder and brain aging has been established." (PMID 39765817, 2024). "Insulin improves cognitive impairment in Wistar rats by reducing brain oxidative stress and increasing antioxidant systems such as SOD, catalase, and GSH." (PMID 36233271, 2022). "Conversely, TDF-AgNPs administration to diabetic rats improved cognitive deficits; and increased glutathione, SOD, and CAT, but reduced PFC malondialdehyde and IL-1β concentrations." (PMID 35122679, 2022). "To evaluate the effects of THPH on the regulation of the oxidative stress system in the brain of cognitive impairment mice, we detected the parameters such as GSH, SOD, MDA and CAT, which were closely related to oxidative stress." (PMID 34945680, 2021). "In streptozotocin-induced diabetic rats, huperzine A has shown to attenuate cognitive defects by increasing the levels of glutathione peroxidase, BDNF, catalase, and SOD while simultaneously inhibiting, CAT, MDA, TNF-α, NF-κB, AChE IL-6, and caspase-3." (PMID 29896105, 2018). "The activities of the antioxidant enzymes CAT and SOD were significantly diminished due to SCOP- treated cognitive impairment." (PMID 30050927, 2018). "In the study by Della and colleagues (2012), it was emphasized that tianeptine, which improves stress-related cognitive impairment, may alleviate oxidative stress by increasing SOD and CAT activities in an animal model." (PMID 40722762, 2025). "Its administration enhanced catalase activity and GSH levels while reducing hippocampal NF-κB and MMP-9 expression, highlighting the complex interplay between oxidative stress, inflammation, and cognitive impairment." (PMID 41155598, 2025). "It has been reported that the prescription of betacyanins derived from purslane to mice with learning and memory impairment lowered cognitive impairment by increasing superoxide dismutase (SOD), catalase (CAT), glutathione reductase (GR), and glutathione peroxidase (GPx) amounts in mice brain." (PMID 36594059, 2023). "Previous findings confirmed that administration of EA prevents cognitive impairment through attenuation of the brain lipid peroxidation and prevented waning of the superoxide dismutase (SOD), glutathione (GSH), and catalase (CAT) activity in streptozotocin-induced rats." (PMID 35860668, 2022). "A previous study found that a probiotic mixture could significantly increase the activities of SOD and CAT, as well as decrease MDA content, which eventually ameliorated the cognitive deficit in a d-gal-induced aging mouse model." (PMID 35057509, 2022). "In an intracerebroventricular-streptozotocin-induced AD-type model of rats with cognitive impairment, naringenin increases GST, glutathione peroxidase (GSH-Px), glutathione reductase (GR), superoxide dismutase (SOD), and catalase (CAT) to detoxify 4-HNE in the hippocampus." (PMID 31963301, 2020).
Cognitive impairment (continued). "Huperzine A attenuates cognitive defects in streptozotocin-induced diabetic rats by increasing the levels of ChAT, BDNF, SOD, glutathione peroxidase, and catalase while simultaneously inhibiting AChE, MDA, CAT, NF-κB, TNF-α, IL-1β, IL-6, and caspase-3." (PMID 26075266, 2015). "However, in an intracerebroventricular-streptozotocin-induced Alzheimer’s model in rats with cognitive impairment, naringenin was found to enhance GSH, glutathione reductase (GR), glutathione peroxidase (GSH-Px), SOD, and CAT to detoxify 4-HNE in the hippocampus." (PMID 40616709, 2025). "Furthermore, significantly elevated plasma Aβ and lipid peroxidation levels were found in CKD patients with cognitive impairment, alongside reduced levels of superoxide dismutase (SOD), catalase (CAT), glutathione peroxidase (GPx), and reduced glutathione (GSH)." (PMID 40362589, 2025). "The present study was undertaken to evaluate the effect of chronic treatment with the natural occurring polyphenol phloridzin, a potent nonselective SGLTI, on STZ-icv-induced cognitive deficit and its effect on duodenal Aβ 1-42 and catalase homeostasis in a sporadic rat model of Alzheimer’s disease." (PMID 37189641, 2023). "Diabetic rats administered TDF exhibited cognitive deficits; and increases in blood glucose, malondialdehyde, and interleukin-1 beta (IL-1β) levels, which correlate with decreases in glutathione level, and superoxide dismutase (SOD) and catalase (CAT) activities." (PMID 35122679, 2022). "In addition, our study showed that THPH administration significantly reduced the oxidative stress response in brain of mice with cognitive impairment induced by scopolamine, including markedly increasing the activities of SOD and CAT, raising GSH level, and reducing the content of MDA." (PMID 34945680, 2021). "Indeed, it has been shown to improve cognitive deficits, suppress vascular aging and inflammation in elderly mice, and attenuate neuronal aging both in vitro and in vivo by downregulating the expression of p16 and p21 and upregulating antioxidant enzymes, including SOD1, CAT and GPx." (PMID 35883714, 2022).
metabolic syndrome (61 papers, 2012 to 2026). A cluster of metabolic risk factors for CARDIOVASCULAR DISEASES and TYPE 2 DIABETES MELLITUS. "For instance, expression of catalase in mitochondria reduces autophagy and hypertrophy in angiotensin II–treated mouse hearts and improves contractile dysfunction in mice with metabolic syndrome caused by high-fat, high-sucrose diet." (PMID 34710060, 2021). "Furthermore, it was postulated that catalase activity could be involved in the mechanism, since it has been shown that 3-Amino-1,2,4-Triazole, a catalase inhibitor, induces quick fat loss in mice with high fat-induced metabolic syndrome." (PMID 39273464, 2024). "In contrast, supplementation with bergamot leaf extract improved glucose levels, dyslipidemia, lipid peroxidation, and hepatic triglyceride levels and also increased the activity of the antioxidant enzyme catalase in the liver." (PMID 40427425, 2025). "Targeting mitochondria to overexpress catalase in mice extends lifespan and alleviates oxidative stress in diseases such as metabolic syndrome." (PMID 36824356, 2023). "These complications occurring in the context of dyslipidemia are due in part to a decrease in the expression and activity of antioxidant enzymes such as catalase (CAT) and superoxide dismutase (SOD), which enhances OS." (PMID 34368206, 2021). "The RE-induced Nrf2 activity enhances the antioxidant defense system in rats with metabolic syndrome, evident by increased expression of catalase (CAT), SOD isoforms, peroxidases, glutathione-S-transferase, and glutathione reductase." (PMID 32197410, 2020). "BMI and metabolic syndrome have been also associated with oxidative stress (MDA, MPO, CAT) and pro-inflammatory markers (IL-6, high sensitivity C-reactive protein)." (PMID 32824349, 2020). "Flavanone (naringenin) was most effective at restoring hepatic function (ALT activity) and reducing dyslipidemia (serum and hepatic TC level), oxidative stress (CAT activity), and apoptosis." (PMID 30441755, 2018). "P-407-induced dyslipidemia was associated with elevated liver malondialdehyde (MDA) and nitric oxide (NO), and a decrease in reduced glutathione (GSH), superoxide dismutase (SOD) and catalase (CAT) (p < 0.001)." (PMID 39458984, 2024). "In addition, metabolic syndrome rats induced by HCHF diet showed the significant decrease in CAT activity in adipose tissue of both visceral and subcutaneous areas and in plasma (p value < 0.001 all, compared to naïve control)." (PMID 31827683, 2019). "In accordance with our results, Bouzidi and coworkers reported an increased CAT activity in patients with dyslipidemia and chronic renal failure after n-3 PUFA supplementation, assuming a greater protection against oxidative stress and prevention of vascular complications." (PMID 22621246, 2012). "However, the inflammation and oxidative stress in metabolic syndrome is described as a chronic low-grade state, which may be the reason for the unchanged plasma catalase activities in H rats, and the undetectable plasma IL-6 concentrations." (PMID 30287733, 2018). "Considering that adipose tissue and liver are the most important organs for lipid metabolism and that catalase is highly expressed in WAT as well as liver, it is speculated that catalase deficiency in WAT and liver may play critical roles in dyslipidemia in CKO mice." (PMID 27597806, 2016). "In a previous study, butterfly pea flower demonstrated the reductions in multiple metabolic syndrome parameters, such as improving lipid profile, blood glucose, SOD, and CAT in rats with a high‐fat, high‐carbohydrate diet." (PMID 41510340, 2026). "The toxicity is observed in the form of dyslipidemia, oxidative stress (increased MDA and NO and decreased GSH, SOD, CAT, and GST), and inflammatory responses (increased TNF-α and IL-6)." (PMID 40407528, 2025).